BRCA1 (BRCA1 DNA repair associated)
Diseases named in the same sentence as BRCA1 in open-access papers (continued):
Sharing a sentence is not in itself a finding about the gene and the disease.
cancer (continued). "Although currently theoretical, this would further widen the therapeutic index by selectively increasing the radiosensitivity of BRCA1/2-mutated cancer cells, which consistently harbor biallelic function loss and consequent homologous recombination deficiency." (PMID 38799106, 2024). "In BRCA1/2-deficient cancer cells, extensively degraded replication forks can be rescued through distinct fork recovery mechanisms that also promote cell survival." (PMID 38943334, 2024). "Several models have been proposed to explain why PARP inhibition selectively induces synthetic lethality in BRCA1/2- or HR-deficient cancer cells." (PMID 39007266, 2024). "Large case-control studies were performed using different gene sets, for example, eight cancer predisposition genes excluding BRCA1/2 genes, to analyze the contribution of moderate risk genes such as ATM, PALB2, CHEK2, and so on." (PMID 39684352, 2024). "Gene deficiency in any of these DSBRR genes, or ‘BRCAness’, a phenotype first defined in BRCA1/2-mutated cancers, impairs DSB repair and promotes PARPi synthetic lethality." (PMID 38714348, 2024). "Elevated interferon signaling has been observed in various BRCA1-null or mutated cancers and epithelial cells." (PMID 39159817, 2024). "Once resistance to endocrine alternatives is established, chemotherapies and targeted treatments in selected patients (ie, patients whose cancers are PI3KCA or BRCA1/2 mutated) are indicated." (PMID 38206277, 2024). "Cancer cells with HR deficiency (e.g., with BRCA1/2 mutations) are uniquely sensitive to DNA crosslinking agents and PARP inhibitors, but some of these cells acquire de novo resistance to these drugs due to concomitant loss of the NHEJ pathway." (PMID 38172598, 2024). "L-Leucine activates mTOR pathway, which has been suggested as a therapeutic target for BRCA1-deficient cancer." (PMID 38468344, 2024). "Multivariate analysis revealed that family members with cancer (OR = 2.36, 95% CI 1.00–5.54, p = 0.049) as one of the independent predictors for BRCA1/2 mutation." (PMID 38167124, 2024). "Cancer cells from patients who carry a disease-causing BRCA1 or BRCA2 mutation are incapable of repairing double-strand DNA breaks via the homologous recombination (HR) repair pathway." (PMID 38398132, 2024). "Based on this initial model, PARPis have been found selectively toxic to cancer cells harboring BRCA1 or BRCA2 (BRCA1/2) mutations or showing HR deficiency." (PMID 38961202, 2024). "Talazoparib and Olaparib are both oral PARP inhibitors that interfere with the PARP enzyme, making it more difficult for cancer cells with BRCA1 or BRCA2 mutations to repair DNA damage, reducing the likelihood of cancer survival and progression." (PMID 38327984, 2024). "Mutations in the breast cancer gene 1 (BRCA1) and breast cancer gene 2 (BRCA2) genes significantly increase the risk of breast and ovarian cancers." (PMID 39767566, 2024). "Loss of functional BRCA proteins is linked to increased cancer susceptibility because of the central roles of BRCA1/2 in preserving genome stability." (PMID 38943334, 2024). "This vulnerability to PARP inhibitors mirrors the susceptibility observed in HDR-deficient cancer cells, such as BRCA1/2-deficient breast cancers." (PMID 38824133, 2024). "Mutations in BRCA1 allow cells with DNA damage to continue dividing, thereby increasing the risk of cancer development." (PMID 39061909, 2024). "Interventions for risk assessment and genetic counselling and testing for BRCA1/2-related cancer are now part of public health strategies." (PMID 39195440, 2024). "Individuals carrying BRCA1 mutations were also found to be at higher risk of developing other types of cancer, such as pancreatic and cervical." (PMID 38534919, 2024). "TNBC is typically observed (75%) in women who carry a mutation in the Breast cancer type 1 susceptibility protein, BRCA1, gene." (PMID 38499540, 2024).
cancer (continued). "Specifically, PARPi-induced cGAS-STING activation within BRCA1-deficient cancer cells results in the intratumoral production of IFN-I, subsequent immune cell infiltration, and T cell-dependent anti-tumor immunity." (PMID 38459088, 2024). "As such, UFL1 can be considered a biomarker of BRCA1-deficient cancer cells and thus indicate the likely response to chemotherapy." (PMID 38657865, 2024). "This is particularly relevant for women who already face a higher cancer risk, especially carriers of BRCA1/2 pathogenic variants." (PMID 38892081, 2024). "We took a blood sample from 989 female BRCA1 mutation carriers who were initially unaffected by cancer and followed them for a mean of 7.5 years thereafter." (PMID 38790714, 2024). "What do you think of the idea of offering a psychological intervention to women who were treated for cancer and are carriers of a BRCA1/2 mutation?" (PMID 38192174, 2024). "It is well established that germline BRCA1 mutations are associated with familial breast and ovarian malignancies." (PMID 38542081, 2024). "There have been no studies examining the association of lead with the risk of cancer in BRCA1 mutation carriers." (PMID 38732616, 2024). "Some kind of cancers, such as breast and ovarian cancers, have mutations in the BRCA1 or BRCA2 genes that compromise their homologous recombination ability." (PMID 38327984, 2024). "PARP-is trap PARP on DNA at sites of single-strand breaks (SSBs), hindering repair and promoting their conversion to double-strand breaks in HR-deficient cancers like BRCA1/2-mutant and RAD51-mutant tumors, inducing apoptosis." (PMID 39123379, 2024). "Risk-reducing salpingo-oophorectomy (RRSO) is a prophylactic surgery of the reproductive organs, which is frequently conducted by the age of 40 to lower the occurrence of cancer in women with BRCA1/2 mutations." (PMID 39201170, 2024). "These BRCA1 mutations impair HR, making these cancers initially sensitive to PARP inhibitors but also capable of developing resistance through mechanisms that restore HR functionality." (PMID 39456202, 2024). "CRISPR-based gene editing can also be used to repair genetic mutations that cause cancer, such as in the case of inherited forms of cancer caused by BRCA1 and BRCA2 mutations." (PMID 38195537, 2024). "Although many cases of these cancers are sporadic, there is a subset of individuals who have a genetic predisposition to developing BOCs due to germinal mutations in the BRCA1/2 DNA repair associated genes." (PMID 38279352, 2024). "Studies have shown that POLQ is upregulated in HR-deficient cancers, including those with BRCA1/2 PVs, and inhibiting POLQ leads to micronuclei formation and IFN signaling." (PMID 39682099, 2024). "This is particularly true for BRCA1 mutated cancers, where HRD-H was predicted significantly better than in BRCA1 wildtype cases." (PMID 39379982, 2024). "Since the repair of these lesions requires an intact homologous recombination (HR) pathway, HR-deficient cancers (e.g., due to dysfunctional BRCA1/2) amass chromosomal aberrations resulting in cell death by mitotic catastrophe after PARPi treatment." (PMID 38360994, 2024). "Cisplatin followed by olaparib, larotrectinib or entrectinib, and pembrolizumab are recommended for BRCA1/2- or PALB2-mutated cancers, NTRK gene-fusion-positive cancers, and MSI-H/dMMR cancers respectively." (PMID 38467634, 2024). "Our work reveals a previously unappreciated role of the RAD18, UBC13, PALB2 and RNF168 pathway in replication fork recovery in BRCA1-deficient cancer cells." (PMID 38943334, 2024). "Pathogenic mutations in BRCA1 (BReast CAncer gene 1) confer high risks of both breast (up to 70%) and ovarian (up to 40%) cancers." (PMID 39061909, 2024). "In women carrying a germline pathogenic variant in BRCA1/2, there are several risk management strategies recognized as effective and cost-effective to mitigate the increased cancer risk, such as Risk-reducing salpingo-oophorectomy for the prevention of OC." (PMID 38386807, 2024).
cancer (continued). "Testing for BRCA1/2 mutations should be performed when an individual’s personal or family history suggests an inherited cancer susceptibility and when the results of the testing are expected to have an impact on the decision making." (PMID 39195440, 2024). "BRCA1 mutation carriers are at a higher risk of developing breast, ovarian, prostate, and other types of cancer." (PMID 38499540, 2024). "This approach relies on the idea of synthetic lethality, where the inhibition of PARP1 in cancer cells with defective DNA repair mechanisms (such as BRCA1/2 mutations) leads to cell death, while normal ones with intact DNA repair pathways are less affected." (PMID 39456202, 2024). "Cancer cells with BRCA1/2 deficiencies are sensitive to poly (ADP-ribose) polymerase (PARP) inhibitors." (PMID 39085400, 2024). "In normal cells, mutations or defects in genes related to DNA repair, such as BRCA1, are well known to be associated with a high risk of cancer." (PMID 39125994, 2024). "Because ALDH1A3 is a normal stem and cancer stem cell marker, these results suggest that breast epithelial cells in the normal breasts of BRCA1 mutation careers have inherently higher stem cell activity." (PMID 38059556, 2024). "Among the women with mutations in BRCA1, the median age at diagnosis was 48 years old, and 12 had a family history of cancer." (PMID 38641594, 2024). "Taken together, these data indicate that reconstitution of Gata3 in Brca1-deficient cancer cells restores the efficiency of DNA damage repair and suppresses mesenchymal differentiation in inhibition of tumorigenesis." (PMID 38627785, 2024). "The process of risk assessment and genetic counselling and testing for BRCA1/2-related cancer is undoubtedly of extreme complexity both in technical terms and from the perspective of the variety of actors potentially involved." (PMID 39195440, 2024). "For example, studies have shown that CRISPR-Cas9 can be utilized to correct BRCA1 mutations in human cells, demonstrating the potential for this technology in cancer therapy." (PMID 38195537, 2024). "The roles of BRCA1, BRCA2, and ATR in cancer susceptibility, cyclins and cell cycle regulation, BRCA1-dependent Ub ligase activity, polyadenylation of mRNA, and Sonic Hedgehog receptor Ptc1 regulating cell cycle were the most enriched pathways in BioCarta." (PMID 39765633, 2024). "Cancer biology research highlighted the role of BRCA1/2 mutations and homologous recombination deficiency (HRD), which opened the field for targeted therapies such as poly (ADP-ribose) polymerase (PARP) inhibitors (PARPi)." (PMID 38409030, 2024). "Increased expression of OLA1 in cancer cells appears to enhance their survival by interacting with BRCA1 and BRCA1-associated RING domain proteins (BARD1)." (PMID 38889130, 2024). "In summary, our study did not prove that blood zinc levels are associated with the risk of cancers among BRCA1 carriers." (PMID 38790714, 2024). "Authors suggested that the loss of BRCA1 increased unliganded ER activation increasing cancer risk; however, it was a compensatory activation attributed to the defective liganded activation." (PMID 38672654, 2024). "Follow-up studies will be imperative to delineate the molecular differences underpinning distinct fork recovery mechanisms in BRCA1- versus BRCA2-deficient cancer cells." (PMID 38943334, 2024). "Familial mutations in BRCA1/2 genes significantly increase the lifetime risk of breast (up to 85%) and ovarian (15%–56%) cancers in carriers." (PMID 39007266, 2024). "It is important to emphasize how the use of the multigenic panel, including 27 genes associated with hereditary cancers, allowed us to increase the detection rate of unaffected individuals with mutations in genes beyond BRCA1 and BRCA2." (PMID 39001389, 2024).
cancer (continued). "BRCA1/2 reversion mutations have first been studied using in vitro cancer cell lines, demonstrating the restoration of open reading frame and HR activity that confer platinum and PARPi crossresistance." (PMID 38544832, 2024). "Intratumoral STING activity is essential in mediating the efficacy of PARP inhibitors (PARPi) which are used in the treatment of cancers harboring BRCA1 deficiency." (PMID 38459088, 2024). "Healthy individuals and cancer patients who are carriers of germline pathogenic variants in BRCA-1/2 genes face multiple reproductive challenges that require appropriate counseling and expertise." (PMID 39176249, 2024). "This study examines the antioxidant properties of Zn and Cu, specifically focusing on the blood Zn/Cu ratio as a potential marker for cancer risk among BRCA1 mutation carriers." (PMID 39061909, 2024). "Our data point to an important role of the POLA complex in PARPi-induced fork acceleration and reveal a rationale for targeting the POLA complex in BRCA1-deficient cancer cells." (PMID 39191785, 2024). "The evidence indicates that BRCA1/2 mutation carriers benefit from early cancer detection and prevention strategies." (PMID 39590130, 2024). "STING-mediated production of IFN-I in a cancer cell-intrinsic fashion has been recently shown to be essential for the anti-tumor effects of PARPi treatment in BRCA1-deficient TNBC11." (PMID 38459088, 2024). "Poly(ADP-ribose) polymerase (PARP) inhibitors are targeted therapies that accumulate DNA damage by interfering with DNA repair mechanisms and are approved for treating several cancers with BRCA1/2 mutations." (PMID 39062738, 2024). "Women who carry a BRCA1 or BRCA2 mutation have elevated risks for many types of cancer, including breast, ovarian, fallopian tube and peritoneal cancers." (PMID 38741145, 2024). "In the case of HR deficiency (HRD), such as a loss of function mutation in the BRCA1/2 gene, the accumulation of unrepaired DBSs leads to genomic instability and cancer cell death." (PMID 38544832, 2024). "The application of the concept was first validated clinically in cancers with BRCA1 and BRCA2 mutations leading to HR repair deficiency." (PMID 39156700, 2024). "Of course, such cancers would need to be identified by the presence of a biomarker (similar to BRCA1/2 mutations as an indication for treatment with PARP inhibitors)." (PMID 38478595, 2024). "Our work reveals another cancer type potentially targeted by PARPi in addition to canonical BRCAness cancers carrying BRCA1/2 mutations." (PMID 38263342, 2024). "Next-generation sequencing (NGS) panel tests have identified mutations in other cancer-associated genes in BRCA1/2-negative patients with suspected HBC, sometimes more than doubling the mutation detection rate." (PMID 39741970, 2024). "PARP inhibitors have therefore been applied as a targeted therapy for cancers harboring BRCA1/2 mutations." (PMID 38638566, 2024). "Investigating the quality and results of the programme is necessary because the best practices in risk assessment and genetic counselling and testing for BRCA1/2-related cancer and the challenges they encounter should be identified and shared." (PMID 39195440, 2024). "Implementing this screening is critical as women who carry a BRCA1/2 mutation have significantly increased lifetime risks for breast (50–80%) and ovarian (10–40%) cancer." (PMID 39416933, 2024). "We found that 15 KIF family proteins have various connections with 11 of the ACMG cancer-associated genes, including BRCA1 and BRCA2." (PMID 39409999, 2024). "We also acknowledge investigators of the Genetic Modifiers of Cancer Risk in BRCA1/2 Mutation Carrier (GEMO) Study from the National Cancer Genetics Network UNICANCER Genetic Group, France." (PMID 38834293, 2024). "Understanding the structure and function of BRCA1 is crucial for developing targeted therapies and improving cancer risk assessment." (PMID 38543119, 2024).
cancer (continued). "This raises concerns as to the proper implementation of risk assessment and genetic counselling and testing for BRCA1/2-related cancer, especially with respect to between-service coordination." (PMID 39195440, 2024). "Cancer cells with BRCA1 mutations can overcome the toxicity of PARP inhibitors by loading DSB with BRCA1-independent RAD51, thereby overcoming drug resistance." (PMID 38910895, 2024). "As a result, the NCCN (National Comprehensive Cancer Network) guidelines suggest risk-reducing strategies for unaffected BRCA1/2 mutation carriers, including cancer surveillance, chemoprevention, and risk-reducing surgery." (PMID 39590130, 2024). "Understanding these influences is particularly important for individuals with a heightened risk of cancer, such as BRCA1 mutation carriers, who face a significantly increased lifetime risk of breast (up to 70%) and ovarian (up to 40%) cancer." (PMID 39061909, 2024). "Understanding the intricate interplay between BRCA1 and P21 is crucial for developing targeted therapies and interventions for individuals with BRCA1 mutations or related cancers." (PMID 38195537, 2024). "If either the ER-alpha or BRCA1 protein function suffers damage, the result will be genomic instability and increased cancer risk." (PMID 38672654, 2024). "We also show that RAD18 protein levels are elevated in primary and metastatic BRCA1-deficient cancer tissues relative to BRCA wild-type tumors." (PMID 38943334, 2024). "These inhibitors work well in cancers that have flaws in homologous recombination (HR) DNA repair, especially those caused by BRCA1 or BRCA2 mutations." (PMID 39001539, 2024). "Poly(ADP-ribose) polymerase (PARP) inhibitors (PARPis) selectively kill BRCA1/2-deficient cancer cells by inducing synthetic lethality, providing an effective biomarker-guided strategy for targeted cancer therapy." (PMID 39007266, 2024). "It is well established that cancer risk is modified by family history (BRCA1/2; PALB2; RAD51C and RAD51D (RAD51C/D))." (PMID 38443545, 2024). "Of the 9,330 adult Latinas in Georgia that completed cancer genetic FH screening, 9,066 (97.17%) women screened negative, and 264 (2.83%) screened positive (i.e., FH suggestive of higher risk for carrying BRCA1/2 mutations compared to the general population)." (PMID 39416933, 2024). "Positive BRCA1 expression was observed in 28.57% of patients and was associated with advanced cancer stages." (PMID 39742378, 2024). "Originally, the concept of BRCAness was used to describe the HRD signatures that occur in BRCA1/2-deficient cancer cells, which are characterized by hypersensitivity to PARPi." (PMID 38745917, 2024). "Treatment for BRCA1/2-deficient cancers frequently involves the use of PARP inhibitors, which exhibit substantial anticancer effects in this context that considerably outweigh those for BRCA1-expressing tumors." (PMID 38672570, 2024). "HBOC is linked to heterozygous and germline pathogenic variants (PVs) in cancer predisposition genes, with BRCA1 and BRCA2 being the most commonly affected genes." (PMID 38928478, 2024). "The tissue-specific patterns of BRCA1-associated cancers emphasize the importance of ovarian hormones, particularly progesterone, in pathogenesis." (PMID 38543119, 2024). "Mutations in the tumor-suppressor genes BRCA1 and BRCA2 resulting in BRCA1/2 deficiency are frequently identified in breast, ovarian, prostate, pancreatic, and other cancers." (PMID 39007266, 2024). "Various cancer predisposition genes, including BRCA1, BRCA2, and p16/CDKN2A, have already been identified in high-risk pedigrees." (PMID 38894738, 2024). "Among these mechanisms, the restoration of HR caused by re-established BRCA1/2 function has been detected in human cancer." (PMID 38360994, 2024). "BRCA1/2 genes are somehow promiscuous with respect to the spectrum of associated tumors; therefore, many other cancer types are slightly enriched by BRCA1/2 mutation carriers." (PMID 38612902, 2024).